CRY1 (cryptochrome circadian regulator 1)
Diseases named in the same sentence as CRY1 in open-access papers (continued):
Sharing a sentence is not in itself a finding about the gene and the disease.
tumor (46 papers, 2010 to 2025). "Several clock genes have also been linked to altered CRC progression either as tumor suppressors (e.g., per2) or oncogenes (e.g., cry1)." (PMID 40868120, 2025). "In colorectal cancer cells, increased CRY1 was associated with tumor advancement." (PMID 38892035, 2024). "Thus, tumor-associated CRY1 appears to be essential for cellular proliferation but alone is insufficient to drive a hyperproliferative phenotype." (PMID 33452241, 2021). "Additionally, Cry1 and Cry2 mutations alter tumor formation." (PMID 37024472, 2023). "This study does not include in vivo functional validation of miR-150-5p’s effect on myb, bcl2, and cry1 expression or tumor growth." (PMID 40868120, 2025). "Its tumor-promoting role in CRC progression was demonstrated by cry1-induced cell proliferation and inhibited apoptosis in HT29 and SW480 CRC cell lines." (PMID 40868120, 2025). "Here, we identified the core circadian gene Cryptochrome1 (Cry1) as a potential tumor suppressor in HCC." (PMID 41142939, 2025). "A role of miR-150-5p/myb interference in CRC tumor growth has been demonstrated previously in nude mice; however, the tumor suppressor role of miR-150-5p mediated via bcl2 and cry1 expression needs to be addressed in the next studies." (PMID 40868120, 2025). "KEGG analysis demonstrated that circadian rhythm pathway was significantly enriched on both 3 d and 7 d, genes related to disease/tumor, including Tns4 and Neu1 (upregulated), as well as Npas2 and Cry1 (downregulated), exhibited obvious changes." (PMID 39727670, 2025). "This decrease was accompanied by an increase in the expression of clock gene cry1 in tumor compared to adjacent tissue." (PMID 40868120, 2025). "Another study revealed that CRY1, a tumor-specific AR signaling pathway target gene, is involved in androgen-regulated DNA repair and plays an important role in the growth of androgen-resistant prostate cancer (CRPC)." (PMID 39011396, 2024). "Overall, the roles of Cry1 and Cry2 in regulating tumor formation or progression are distinct and unique; therefore, their potential functions in tumor development must be examined separately." (PMID 37024472, 2023). "The tumour oncogenic role is usually attributed to the cry1 gene, whereas per2 is recognized as a tumour suppressor." (PMID 37831728, 2023). "Per1-/-, Per2-/-, Cry1-/-, Cry2-/- andBmal1-/- mice presented with increased spontaneous and radiation-induced tumor development." (PMID 39282509, 2023). "The use of Cry1/2 agonists induced anti-tumor effects suggesting that GSCs are sensitive to cry1/2 activity." (PMID 35216153, 2022). "In sum, these studies identify a novel, tumor-specific mechanism by which hormones regulate DNA repair and are the first to delineate the molecular framework used by CRY1 in PCa progression." (PMID 33452241, 2021). "Previous studies have shown a decrease in CRY1 in tumours compared to normal mucosa, which would agree with our results." (PMID 34440171, 2021). "Critically, findings herein strongly link tumor-specific CRY1 induction with poor outcome and altered DNA repair processes." (PMID 33452241, 2021). "Combined, these findings identify CRY1 as a tumor specific, AR-induced effector of poor outcome in PCa and identify entirely new functions of CRY1 to temporally control HR and the response to genomic insult." (PMID 33452241, 2021). "Similar to results observed on Cry1 expression, IDH1 mutated U-87MG cells showed lower levels of Cry2 than wild-type cells with implications in tumor proliferation." (PMID 34361055, 2021).
tumor (continued). "Studies herein identify an unexpected, temporally modulated mechanism of DSB repair regulation, mediated by tumor-specific, AR-mediated induction of the CRY1 transcriptional regulator." (PMID 33452241, 2021). "Here, the circadian factor CRY1, an evolutionally conserved transcriptional coregulator, is identified as a tumor specific regulator of DNA repair." (PMID 33452241, 2021). "Like other core circadian clock proteins, there are discrepancies in the literature regarding the expression of CRY1 in tumour tissue versus normal mucosa." (PMID 34440171, 2021). "In contrast, PER1 and CRY1 were up-regulated in tumour and neighbouring mucosa compared to the normal donor tissue." (PMID 27465361, 2016). "Genetic inactivation of Cry1 and/or Cry2 has also been reported to alter rates of tumor formation, though the reported effects have varied." (PMID 25756610, 2015). "In mouse study, nude mice had more obvious tumor growth after subcutaneously injecting overexpressed CRY1 of human CRC cells compared to that in control group." (PMID 24708606, 2014). "The animal model was used to explore the Cry1 impact on the tumor cellular proliferation ability in vivo." (PMID 23626715, 2013). "The host circadian clock has been reported to play an important role in the endogenous control of tumor progression.Cry1, one member of the Cryptochrome family, has been shown to be essential to the negative arm of the circadian feedback loop." (PMID 23626715, 2013). "In the tumor tissue, CRY1, TIM, and GPER1 expressions showed circadian rhythms in both the control and the TRF groups, but the circadian rhythm of TIM expression was more robust in the TRF group, while CRY2 were acyclic in the control group and FBXL3 were acyclic in the TRF group." (PMID 37924048, 2023). "However, when exploring circadian clock proteins functions in tumor formation and progression, most studies investigated Cry1/2 simultaneously, assuming that their roles were the same and even redundant." (PMID 37024472, 2023). "It is worth mentioning that the impaired expression of CRY1 was associated with elevated levels of pro-inflammatory cytokines, such as tumor necrosis factor alpha (TNF-α), which can mediate pro-survival or pro-death signals after tumor target recognition." (PMID 35897788, 2022). "Together, these observations nominate CRY1 as a tumor specific, AR-regulated target gene." (PMID 33452241, 2021). "In addition, mosaic plots confirm an increase in the number of patients developing MM at 3 and 5 years when they received therapy (radiotherapy and/or chemotherapy) and had high CRY1 expression in tumours." (PMID 34440171, 2021). "CRY1 was significantly increased in tumour cytoplasm and neighbouring mucosal cells." (PMID 27465361, 2016). "It is also possible that the clock genes Clock, Cry1 and Bmal1, which are involved in the circadian control of whole-body glucose metabolism, may have contributed to the circadian regulation of tumor glucose metabolism in our investigation." (PMID 25099274, 2014). "Expression of cry1 differed between left- and right-sided CRC tumours, and these differences exerted sex-dependent patterns." (PMID 37831728, 2023). "Higher cry1 expression was observed in colorectal liver metastases and in CRC tumour tissue of males compared to that of females." (PMID 37831728, 2023). "Cryptochrome 1 (CRY1) is an evolutionary conserved transcriptional coregulator, identified as a tumor-specific regulator of DNA repair." (PMID 37323834, 2023). "Multiple studies have reported decreasedBMAL1, CRY1-2 and PER1-3, and increasedCLOCK,CSNK1E andTIM in tumor tissue relative to matched healthy mucosa (Honget al., 2014b;Kruglugeret al., 2007;Mazzoccoliet al., 2011,2016;Oshimaet al., 2011;Zenget al., 2014)." (PMID 39282509, 2023). "Numerous studies have shown that circadian rhythm regulators, such as PER2, CLOCK, BMAL1, CRY1, and CRY2, act as tumor suppressors in the liver, ovaries, colon, and lung." (PMID 37524704, 2023).
tumor (continued). "AR is a key driver of PCa, and this study identifies another avenue to promote disease progression through regulation of CRY1, which further enhances DDR to promote genomic instability and tumor growth." (PMID 33452241, 2021). "Additional studies of CRY1 and CRY2 are needed to understand their overlapping and distinct roles in cell division and tumor formation." (PMID 29152229, 2017). "CRY1 (p = 0.01) and CRY2 (p < 0.0001) expression was significantly changed in tumour tissue, as confirmed in a large independent CRC dataset." (PMID 26768731, 2016). "For CRY1, the gene seemed to be equally up- or down-regulated in the samples, and for CRY2, the majority of the samples showed a down-regulation in the tumour tissue." (PMID 27465361, 2016). "After stratifying patients according to the median value of gene expression, subjects with CRY1 (p = 0.042) and CRY2 (p = 0.043) tumour mRNA levels above the median showed poorer survival rates in a Kaplan–Meier analysis of censored data." (PMID 26768731, 2016). "In contrast, lower CRY1 and CRY2 expression was found in tumour tissues located at the transverse colon." (PMID 26768731, 2016). "SCN has a high CRY1 expression level, and mice with removed SCN exhibit enhanced tumor development." (PMID 38892035, 2024). "Inhibition of tumor growth by blue LED light may also be related to the effects of SOCS3 and CRY1/2, which needs further verification." (PMID 36313662, 2022). "Previously, we observed downregulation of cry2 and per2 expression in tumour tissue in comparison to adjacent tissue, and higher expression of cry1 in right-sided tumours but not in left-sided tumours compared to surrounding tissue." (PMID 36361993, 2022). "Similarly to CRY1, although the expression of NR1D2 was reduced in tumour tissue compared to normal mucosa, patients with a higher expression of this protein also had an increased risk of developing LR." (PMID 34440171, 2021). "In one, tumor-free survival of Ink4a−/−, Ras(V12G), Cry1/2−/− mice with no functional clock were used." (PMID 34375638, 2021). "Moreover, the mRNA expression of CLOCK, CRY1, and CRY2 declined in tumor tissues compared with normal tissues (p < 0.001)." (PMID 32681792, 2020). "Additionally, lower CRY1 mRNA levels were found in female CRC patients, while higher CRY1 and CRY2 levels were observed in tumours located at the distal colonic segments (descending and sigmoid colon, rectum)." (PMID 26768731, 2016). "PER1 and CRY1 were both up-regulated in neighbouring and tumour tissue compared to normal mucosa, while PER2 and PER3 were up-regulated in neighbouring mucosa and down-regulated in the tumour tissue." (PMID 27465361, 2016). "High Cry1 protein expression was detected in 101 samples (60.1%) and weak or negative staining was observed in 67 tumor samples (39.9%)." (PMID 23626715, 2013). "Mice lacking Per1 and 2, Cry1 and 2, or one copy of Bmal1, all show increased spontaneous and radiation-induced tumor development." (PMID 20539819, 2010). "Similarly, we do not claim that CRY1 is a tumor suppressor gene because glycolysis is one of the cellular functions controlled by the circadian clock." (PMID 38199564, 2024). "CRY1 and CRY2 mRNA levels were significantly changed in CRC tissue when compared to matched non-tumorous mucosa, and there was a positive linear correlation between mRNA expression levels of both cryptochrome genes, probably indicating a corresponding and parallel alteration in tumour tissues." (PMID 26768731, 2016). "Only Cry2 stimulates the degradation of the critical tumor activator MYC by recruiting it to SCFFBXL3, whereas Cry1 does not." (PMID 37024472, 2023). "Consistently, CRY1 and CRY2 protein levels decreased in tumour tissues compared to the non-tumorous counterpart in a panel of matched specimens." (PMID 26768731, 2016).
tumor (continued). "CRY1 and CRY2 mRNA levels were assessed in 50 pairs of tumour tissue/non-tumorous mucosa comprising 46 well-moderately differentiated (G1-G2) and 4 poorly differentiated-undifferentiated (G3-G4) CRCs." (PMID 26768731, 2016). "CRY1 (median = 0.73, Q1-Q3 = 0.43-1.24, p < 0.01) and CRY2 (median = 0.50, Q1-Q3 = 0.25-0.77, p < 0.001) mRNA levels showed a statistically significant decrease in tumour tissues in comparison to matched non-tumorous tissues." (PMID 26768731, 2016).
infection (7 papers, 2011 to 2025). The state of being infected such as from the introduction of a foreign agent such as serum, vaccine, antigenic substance or organism. "We further showed that nitric oxide (NO), a host-derived stressor encountered during infection, also activated cry1 expression." (PMID 39814688, 2025). "In this study, we found that the expression level of main piRNA-generation genes BMAL1 and CRY1 were significantly downregulated after SVA infection, which indicated that SVA infection did have an effect on circadian rhythm in PK-15." (PMID 37323834, 2023). "In contrast, 12 h after the infection, the mRNA expression level of erw1 in the transgenic Dar Gazi-cry1 line was about two-fold higher than in Dar Gazi-wt, and this difference remained constant up to 48 h." (PMID 34579419, 2021). "Surprisingly, Dar Gazi-cry1 plantlets better tolerated the pathogen infection showed necrotic tissues after 72/96 h." (PMID 34579419, 2021). "Our experiments suggest that the blue-light photoreceptors PHOT1 and CRY1 were downregulated in response to infection." (PMID 28860643, 2017). "In vivo cry1 expression by both isolates was detected at 24 h and 48 h post infection, while tcaA and tcaB expression was only detected by IBL 90 as expected." (PMID 21464948, 2011). "Expression of Bt-encoded cry1, tcaA and tcaB toxin genes was analyzed within L. dispar larvae infected separately with Bts IBL 455 and IBL 90 at time points 24 h and 48 h post infection." (PMID 21464948, 2011). "In addition, we found that the expression levels of the major piRNA-generating genes BMAL1 and CRY1 were significantly downregulated after SVA infection." (PMID 37323834, 2023). "For the detection of B. pseudomallei in environmental samples such as water and soil which are the primary sources of infection, a multiplex assay incorporating BPSS0664 and the cry1 gene as an extraction and amplification control was developed." (PMID 38600514, 2024).
psychiatric disorder (4 papers, 2013 to 2025). A disorder characterized by behavioral and/or psychological abnormalities, often accompanied by physical symptoms. "The two CRY genes have previously been studied in a number of different neurological and psychiatric disorders; CRY1 was reported to be associated with depression, familial delayed sleep phase disorder, and schizophrenia (16, –18)." (PMID 34256648, 2021). "In the present study, we perform an in depth characterization of behaviors relevant to psychiatric disease in Cry1−/−/Cry2+/+, Cry1+/+/Cry2−/−, and Cry1−/−/Cry2−/− mice." (PMID 24187535, 2013).
metabolic disease (3 papers, 2020 to 2022). A congenital disorder (due to inherited enzyme abnormality) or acquired (due to failure of a metabolically important organ) disorder resulting from an abnormal metabolic process. "Dysfunction of CRY1 and CRY2 isoforms has been associated with a host of diseases, such as sleep phase disorder and metabolic diseases." (PMID 35153842, 2022). "In whole-body Cry1 and Cry2, as well as in liver-specific Arntl and Reverbα/β knockout mice, TRF protected mice from excessive weight gain and metabolic diseases compared to both WT and clock gene KO mice that were fed ad libitum." (PMID 34836101, 2021).
adenocarcinoma (1 paper, 2021). A common cancer characterized by the presence of malignant glandular cells. "These observed enrichments and related pathway analyses provide the first insight into genome-wide CRY1 activity in adenocarcinomas and reveal functions beyond circadian regulation linked to oncogenic factors." (PMID 33452241, 2021).
bacterial infection (1 paper, 2022). "In the same studies, a specific function was played by PHYB and CRY1 photoreceptors, considering that in transgenic plants the first photoreceptor enhanced the gene expression of PR1 5- to 15-fold, and CRY1 enhanced plant resistance to the Erwinia amylovora bacterial infection." (PMID 35406824, 2022).
cardiovascular diseases (1 paper, 2023). "Numerous studies found an inverse association between the higher score of AHEI cardiovascular risk factor and as mentioned, CRY1 rs10861688 is associated with cardiovascular disease." (PMID 37580741, 2023).
colorectal (1 paper, 2021). "In our study cohort, we found a significant underexpression of PER1/2/3, CRY1/2 and NR1D1 proteins in CRC versus normal tissue, indicating an important role of these genes in colorectal carcinogenesis." (PMID 34440171, 2021).
CRY1 also shares sentences with these, for which no sentence is quoted: glioblastoma (2 papers); Glomerular sclerosis (2); Parkinson disease (2); rheumatoid arthritis (2); acute lymphoid leukemia (1); acute myeloid leukemia (1); adenoma (1); brain tumors (1); breast tumor (1); cardiomyopathy (1); cerebral small vessel disease (1); circadian rhythm sleep disorder (1); cystic fibrosis (1); fragile X syndrome (1); gastrointestinal disease (1); gestational diabetes (1); hairy cell leukemia (1); HCMV infection (1); hyperaldosteronism (1); intestinal disease (1); kidney disease (1); liver fibrosis (1); lymphoproliferative disorders (1); malignant brain tumor (1); mantle cell lymphoma (1); metastatic melanoma (1); mucopolysaccharidosis type 2 (1); multiple myeloma (1); neuroblastoma (1); nonalcoholic fatty liver disease (1).
A further 7 diseases each share a sentence with CRY1 in 1 paper.